NDUFAB1 (NADH:ubiquinone oxidoreductase subunit AB1)
Diseases named in the same sentence as NDUFAB1 in open-access papers:
NDUFAB1 is named in the same sentence as 44 diseases in open-access papers, as found by Europe PMC text mining. Sharing a sentence is not in itself a finding about the gene and the disease. The quoted sentences say what the papers report.
Obesity (5 papers, 2017 to 2025). Accumulation of substantial excess body fat. "This protective mechanism is attributed to the role of NDUFAB1 in promoting fatty acid oxidation, thereby reducing lipid deposition and preventing obesity associated with excessive lipid deposition." (PMID 40509084, 2025). "In contrast, the overexpression of NDUFAB1 has been shown to confer protective effects against high-fat-diet-induced obesity and insulin resistance in mice." (PMID 40509084, 2025). "Investigations have demonstrated that the overexpression of NDUFAB1 confers substantial protection against obesity and insulin resistance in murine models." (PMID 38413888, 2024). "Mechanistically, it may propose one of the mechanisms of protection against insulin resistance, especially since it was shown that NDUFAB1 protects against HFD-induced obesity and insulin resistance by enhancing mitochondrial metabolism." (PMID 39596235, 2024). "Specific disruption of the gene expressions of TNFα downstream signals TNFSF11A or NDUFAB1 in the MBH of diet-induced obese mice reverses mitochondrial elongation and reduces obesity." (PMID 28489068, 2017).
Alzheimer disease (4 papers, 2019 to 2025). A progressive, neurodegenerative disease characterized by loss of function and death of nerve cells in several areas of the brain leading to loss of cognitive function such as memory and language. "The Parkinson’s disease and Alzheimer’s disease pathways in the SncaG51D/G51D cortex were significant due to down-regulation of proteins involved in oxidative phosphorylation (NDUFAB1, COX5A, NDUFB8), and in the case of PD dopamine transport (SLC18A2)." (PMID 40574971, 2025). "Notably, we identified that CO therapy decreased the expression of genes encoding ETC complex I genes: NDUFB4, NDUFS2, NDUFAB1, NDUFA6, NDUFB9, also enriched in Parkinson’s, Huntington’s and Alzheimer disease pathways." (PMID 31615996, 2019).
breast carcinoma (4 papers, 2022 to 2025). "Western blot analysis confirmed the upregulation of the NDUFAB1-encoded protein in breast cancer, particularly in the MCF-7 cell line." (PMID 37686016, 2023). "In vitro experiments have further corroborated that NDUFAB1 enhances the migration and proliferation of breast cancer cells." (PMID 40509084, 2025). "Through in vitro experiments, we demonstrated that NDUFAB1 promotes proliferation and migration of breast cancer cells." (PMID 37686016, 2023). "Through in vitro experiments, we provide the first demonstration of NDUFAB1 promoting the migration and proliferation of breast cancer cells." (PMID 37686016, 2023). "In this study, correlation analysis for the expression of prognostic LRGs (FABP7 and NDUFAB1) and immune cell infiltration in breast cancer was also performed using the ssGSEA R package." (PMID 35562758, 2022). "Kaplan–Meier survival analysis results identified the prognostic value of FABP7 and NDUFAB1 in breast cancer patients." (PMID 35562758, 2022). "Based on the prognostic value of FABP7 and NDUFAB1, LASSO Cox regression analysis was used to build a prognostic gene model that revealed that breast cancer patients with high risk scores had a lower overall survival rate than those with low risk scores." (PMID 35562758, 2022). "Prognosis analysis identified the prognostic value of FABP7(Fatty acid binding protein 7) and NDUFAB1(NADH:ubiquinone oxidoreductase subunit AB1) in breast cancer patients." (PMID 35562758, 2022). "Moreover, elevated expression levels of NDUFAB1 have been observed in breast cancer tissues, where high levels of this protein are often associated with poor patient prognosis." (PMID 40509084, 2025). "This provides additional evidence supporting the involvement of NDUFAB1 in breast cancer." (PMID 37686016, 2023). "Previous studies have suggested NDUFAB1 as a potential target for breast cancer." (PMID 37686016, 2023). "The prognostic gene signature constructed with FABP7 and NDUFAB1 was significantly related to immune cell infiltration and could predict the overall survival rate with above average correctness of breast cancer patients." (PMID 35562758, 2022). "By analysing the results, univariate analyses identified the expression of FABP7 and NDUFAB1, and the stage of pT, pN, and pM were the factors that could affect the prognosis of breast cancer patients." (PMID 35562758, 2022). "Furthermore, as lipid metabolism regulators, FABP7 and NDUFAB1 might have the potential to elucidate the mechanism of breast cancer cell invasion and metastasis." (PMID 35562758, 2022). "In conclusion, a thorough investigation of lipid metabolism-related genes was conducted for patients with breast cancer, and a prognostic signature encompassing two biomarkers (FABP7 and NDUFAB1) was discovered for the application of immunotherapy." (PMID 35562758, 2022). "The findings of the prognostic analysis revealed that individuals with breast cancer who had FABP7 downregulation had a low chance of survival (P = 0.001) and upregulation of NDUFAB1 (P = 0.011)." (PMID 35562758, 2022).
asthma (2 papers, 2023 to 2025). "A study demonstrated that NDUFAB1 regulates mitochondrial activity and ROS metabolism via electron transport chain complexes, thereby controlling asthma development, and acts as a hub gene in asthmatic patient samples." (PMID 40337271, 2025). "However, the role of TIMM10 and NDUFAB1 in asthma requires further investigation." (PMID 37152983, 2023).
breast tumours (1 paper, 2023). "Therefore, we analysed the expression of 6 genes from the OXPHOS signature (AIFM1, NDUFV1, NDUFAB1, NDUFA7, NDUFS6 and MRPS12) among the most enriched in metastatic samples, by RT-PCR in specimens of 503 breast tumours patients with a follow-up of 20 years." (PMID 37452026, 2023).
cardiomyopathy (1 paper, 2019). A disease of the heart muscle or myocardium proper. "All these results substantiate that NDUFAB1 ablation-induced cardiomyopathy is mainly caused by impaired assembly of ETC complexes and SCs." (PMID 31366990, 2019). "To investigate the mechanism underlying the cardiomyopathy and heart failure induced by NDUFAB1 ablation, we next assessed changes of cardiac mitochondrial functions at different ages of cKO mice." (PMID 31366990, 2019). "Our findings substantiate that targeting mitochondria for greater bioenergetic capacity and repressed ROS emission with enhanced SC formation is an effective strategy for cardio-protection, and mark NDUFAB1 as a potential therapeutic target for the prevention and treatment of cardiomyopathy." (PMID 31366990, 2019).
Cognitive impairment (1 paper, 2024). Abnormal cognition is characterized by deficits in thinking, reasoning, or remembering. "In participants with cognitive impairment, the expression levels of KEGG:M00146’s NDUFA2, NDUFA3, NDUFA4, NDUFA6, NDUFA7, NDUFA10, and NDUFA12 increased, but the expression levels of NDUFA5, NDUFA4L2, and NDUFAB1 marginally decreased." (PMID 38542318, 2024).
dilated cardiomyopathy (1 paper, 2019). Cardiomyopathy which is characterized by dilation and contractile dysfunction of the left and right ventricles. "Cardiac-specific deletion of Ndufab1 in mice caused defective bioenergetics and elevated ROS levels, leading to progressive dilated cardiomyopathy and eventual heart failure and sudden death." (PMID 31366990, 2019).
heart failure (1 paper, 2019). Inability of the heart to pump blood at an adequate rate to meet tissue metabolic requirements. "Furthermore, the early onset of impaired mitochondrial energetics induced by disrupted assembly of ETC complexes and SCs indicates a causative role of this NDUFAB1 ablation-induced ETC defect in heart failure." (PMID 31366990, 2019). "Together, our findings identify that NDUFAB1 is a crucial regulator of mitochondrial energy and ROS metabolism through coordinating the assembly of respiratory complexes and supercomplexes, and thus provide a potential therapeutic target for the prevention and treatment of heart failure." (PMID 31366990, 2019). "In agreement, our unpublished data showed that NDUFAB1 was decreased in human failing hearts and in mouse hearts after IR, supporting the possibility that NDUFAB1 desregulation may contribute to mitochondrial dysfunction observed in heart failure and IR patients." (PMID 31366990, 2019).
ischemia (1 paper, 2019). A hypoperfusion of the BLOOD through an organ or tissue caused by a PATHOLOGIC CONSTRICTION or obstruction of its BLOOD VESSELS, or an absence of BLOOD CIRCULATION. "Overexpression of Ndufab1 effectively enhanced mitochondrial bioenergetics while limiting ROS production and protected the heart against ischemia-reperfusion injury." (PMID 31366990, 2019).
ischemia reperfusion injury (1 paper, 2024). Adverse functional, metabolic, or structural changes in ischemic tissues resulting from the restoration of blood flow to the tissue (reperfusion), including swelling; hemorrhage; necrosis; and damage from free radicals. "Recent work has shown AAV-mediated overexpression of mitochondrial complex CI core subunit S1 (Ndufs1) and assembly factor Ndufab1 to be cardioprotective against ischemia-reperfusion injury in mice." (PMID 39446877, 2024).
leukemia (1 paper, 2022). A malignant (clonal) hematologic disorder, involving hematopoietic stem cells and characterized by the presence of primitive or atypical myeloid or lymphoid cells in the bone marrow and the blood. "In line with this, the Complex I subunit Ndufab1, which we found to be sensitive to oxidation in fetal cells and with increased oxidation upon MLL-ENL-mediated leukemia initiation, confers greater capacity and efficiency of mitochondrial energy metabolism." (PMID 35640380, 2022).
cancer (6 papers, 2018 to 2023). A tumor composed of atypical neoplastic, often pleomorphic cells that invade other tissues. "Our findings reveal an association between NDUFAB1 and fatty acid elongation, which has been closely linked to various cancers." (PMID 37686016, 2023). "Among the 15 FMGs employed to formulate the FMGsScore, NDUFAB1 exerts the most substantial prognostic influence and remains relatively unexplored in its role within cancer." (PMID 37686016, 2023). "As in NAT10 KD cells, the Remodelin-treated cancer cells showed a remarkable decrease in the mitochondrial respiratory genes NDUFAB1, NDUFA3, and NDUFA7." (PMID 37237981, 2023). "Through TCGA database analysis, we observed high expression of NDUFAB1 in cancer patients." (PMID 37686016, 2023). "Previous studies have indicated the role of NDUFAB1 in cardioprotection, but its specific mechanisms in cancer have not been investigated." (PMID 37686016, 2023).
infection (6 papers, 2011 to 2022). The state of being infected such as from the introduction of a foreign agent such as serum, vaccine, antigenic substance or organism. "At 6 h post infection, the energy metabolism related genes (ATP5G2, COX17, COX5B, GSTP1, NDUFAB1 and NDUFS2) were suppressed." (PMID 23527143, 2013).
tumor (6 papers, 2017 to 2025). "Using the optimal threshold for the NDUFAB1+ tumor cells risk score (NTRS), patients were stratified into high and low NTRS groups, followed by DEGs analysis." (PMID 40688093, 2025). "ST further confirmed the spatial enrichment of C1 NDUFAB1+ subtype in specific regions of GC tissues, underlining their major contribution to tumor development." (PMID 40688093, 2025). "FABP7 and NDUFAB1 were proven to have relevance in immune cell infiltration and tumour mutation burden (TMB)." (PMID 35562758, 2022). "Among these tumor cells, C1 NDUFAB1+ subtype demonstrated elevated expression of genes associated with the cell cycle and indicators of cellular activity, suggesting a more aggressive phenotype." (PMID 40688093, 2025). "Among these, the expression level of ELK4 was particularly prominent in C1 NDUFAB1+ subtype, significantly higher than in other tumor cell subtypes." (PMID 40688093, 2025). "Our study comprehensively revealed the key role of C1 NDUFAB1+ subtype in metabolic reprogramming, tumor progression, and immune microenvironment regulation in GC." (PMID 40688093, 2025). "Through scRNA-seq, we identified four tumor cell subtypes, among which the C1 NDUFAB1+ subtype exhibited significant metabolic activity and stem cell-like properties." (PMID 40688093, 2025). "This study revealed the main significance of the C1 NDUFAB1+ subtype in GC, elucidating its core mechanisms in tumor progression, metabolic reprogramming, and immune evasion." (PMID 40688093, 2025). "First, we ranked the stemness of different tumor cell subtypes using the CytoTRACE method, and the observations supported that C1 NDUFAB1+ subtype possessed increased stemness properties, while C0 MUC5AC+ subtype exhibited lower stemness." (PMID 40688093, 2025). "The specific spatial localization patterns of C1 NDUFAB1+ subtype in tumor tissues were likely closely related to their functional role in tumor progression." (PMID 40688093, 2025). "The gene expression profiles suggested that the expression levels of CDC20, UQCRH, TIMM10, TIMM13, POLR2L, and NDUFAB1 were upregulated in tumor tissue." (PMID 36901944, 2023). "Using tumour immune cell infiltration-related analysis, the results illustrated that FABP7 and NDUFAB1 were significantly correlated with tumour immune cell infiltration." (PMID 35562758, 2022). "Through integrating spatial transcriptomic data with histomorphological information, we not only revealed the spatial distribution characteristics of the C1 NDUFAB1+ subtype but also provided a more comprehensive interpretation of its biological significance in tumor progression." (PMID 40688093, 2025). "In summary, this study systematically elucidated the core mechanisms through which ELK4 mediated tumor progression, metabolic reprogramming, and immune evasion in C1 NDUFAB1+ subtype, offering crucial theoretical foundations for developing precision therapeutic strategies targeting this subtype." (PMID 40688093, 2025). "The high stemness and metabolic activity of C1 NDUFAB1+ subtype suggested that they might play a critical role in driving tumor advancement and resistance to therapy." (PMID 40688093, 2025). "The high stemness and differentiation potential of C1 NDUFAB1+ subtype, coupled with their central role in differentiation trajectories, suggested that this subtype might function as an important driver of tumor progression and heterogeneity." (PMID 40688093, 2025). "The TCGA data confirmed a significant upregulation of the NDUFAB1 gene in tumor samples." (PMID 37686016, 2023). "To better elucidate the involvement of C1 NDUFAB1+ subtype in the TME, we investigated the complex interactions between tumor cells and other cell types." (PMID 40688093, 2025). "Following this, we performed a more detailed examination regarding the tumor cells and classified four tumor cell subtypes based on the expression levels of marker genes (C0 MUC5AC+ subtype, C1 NDUFAB1+ subtype, C2 SRGN+ subtype, C3 HEPACAM2+ subtype)." (PMID 40688093, 2025).
tumor (continued). "Notably, the heterogeneity of EPCs, particularly the identification of four distinct tumor cell subtypes (C0 MUC5AC+, C1 NDUFAB1+, C2 SRGN+, and C3 HEPACAM2+), highlighted the complexity of GC biology." (PMID 40688093, 2025).
neurodegenerative disease (3 papers, 2019 to 2022). A disorder of the central nervous system characterized by gradual and progressive loss of neural tissue and neurologic function. "The proteins with a dual increase in expression and oxidation levels, especially Sdha, Atp5a1, and Ndufab1, have been documented in studies of neurodegenerative diseases." (PMID 36551187, 2022).
metabolic disorders (2 papers, 2019 to 2025). "The study’s findings imply that NDUFAB1 may have the ability to promote adipocyte differentiation, and by controlling adipocyte differentiation, may slow down the metabolic disorders brought on by high NEFA concentrations." (PMID 40509084, 2025). "Our integrated approach aims to elucidate how NEFA exposure modulates NDUFAB1 expression and activity, uncover the molecular mechanisms underlying NDUFAB1’s protective effects against NEFA-induced metabolic dysfunction, and assess its therapeutic potential for bovine metabolic disorders." (PMID 40509084, 2025). "While current evidence indicates NDUFAB1’s involvement in energy metabolism, its potential protective mechanisms against NEFA-mediated metabolic disorders remain unknown." (PMID 40509084, 2025).
heart diseases (1 paper, 2019). "It is thus tempting to speculate that targeting NDUFAB1 to promote ETC complex and SC assembly might afford a potential therapeutic strategy for the prevention and treatment of mitochondrial bioenergetics-centered heart diseases." (PMID 31366990, 2019).
NDUFAB1 also shares sentences with these, for which no sentence is quoted: Parkinson disease (3 papers); bacteremia (2); Insulin resistance (2); anaemia (1); Anxiety (1); anxiety disorder (1); cataract (1); chronic myelogenous leukemia (1); ciliopathies (1); colitis (1); depression (1); diabetes (1); diabetic cardiomyopathy (1); Friedreich ataxia (1); gastric cancer (1); Huntington disease (1); lupus nephritis (1); myopathy (1); neuroblastoma (1); Neurodegeneration (1); ovarian carcinoma (1); Parkinson’s (1); primary immunodeficiency (1); Sepsis (1); skeletal dysplasia (1); spondyloenchondrodysplasia (1).